SFRP1 (secreted frizzled related protein 1)
Diseases named in the same sentence as SFRP1 in open-access papers (continued):
Sharing a sentence is not in itself a finding about the gene and the disease.
cancer (continued). "Several other miRNAs are associated with the Wnt/β-catenin signaling pathways in cancer development, and it will be of interest to determine whether these miRNAs also correlate with SFRP1 expression and whether miR-31 may regulate SFRP1 or vice versa." (PMID 24594839, 2014). "Another cancer-associated gene, SFRP1, is up-regulated in TK6 cells exposed to cadmium." (PMID 21457566, 2011). "In contrast, concomitant DNA methylation of RASSF1A and SFRP1 was detected in the atypical ductal hyperplasia (H3), which unlike the hyperplasias without atypia, is a premalignant lesion associated with risk for progression to cancer." (PMID 19995452, 2009). "The sFRP1 gene is inactivated in many human cancers either as a result of chromosomal deletions or promoter hypermethylation, and loss of sFRP1 expression contributes to a poor prognosis." (PMID 19277043, 2009). "Taken together, our study indicates that the SFRP1 gene is critical for maintaining proper mammary gland development, that reduced levels of SFRP1 results in hyperplastic lesions, and its loss may be a critical event in cancer initiation." (PMID 22928951, 2012). "Our study indicates that SFRP1 gene is critical for maintaining proper mammary gland development, and that reduced levels of SFRP1 results in hyperplastic lesions and its loss may be a critical event in cancer initiation." (PMID 22928951, 2012). "Hypermethylation of the SFRP1 promoter is frequently observed in various cancers and is a common mechanism for downregulating this gene." (PMID 39729237, 2025). "The aim of this study is to evaluate the relationship between the methylation and expression of APC, SFRP1, SFRP2, SFRP4, and SFRP5 genes involved in the Wnt signaling pathway and the risk of cancer development in IBD." (PMID 40521787, 2025). "Expression of DKK1, DKK2, and SFRP1 was verified by IHC staining of clinical specimens of colon normal epithelium, adenomatous, and cancer tissues." (PMID 38334454, 2024). "The expression of Sfrp1 is downregulated in cancer tissues and is presumed to function in cancer suppression by dysregulating cell proliferation and invasion." (PMID 38625488, 2024). "Increased Secreted Frizzled-Related Protein 1 (SFRP1) secreted by fibroblasts can help cancer cells escape from the slow proliferation state and, vice versa, can promote the slow proliferation state." (PMID 38399515, 2024). "An RT-qPCR assay confirmed that the cancer stem-associated transcripts SOX2, OCT4, and NANOG were substantially upregulated by SFRP1 exposure, in both LNCaP and DU145." (PMID 36968194, 2023). "The immunohistochemical staining results reveal a significantly elevated expression of SFRP1 in the paracancerous tissue compared to the cancer tissue." (PMID 37859826, 2023). "The results revealed a significant down-regulation of SFRP1 expression at the mRNA level in cancer tissue compared to paracancerous tissue." (PMID 37859826, 2023). "As a modulator of the Wnt/β-catenin signalling pathway, sFRP-1 has implications in human cancers and neurological diseases." (PMID 39319244, 2023). "Suppression of SFRP1 expression in cancer tissues is well established as a prognostic factor in several types of cancers, including breast, renal, biliary, head and neck, and PDAC." (PMID 37333823, 2023). "A novel mimetic compound has been identified which successfully limited growth of cancer cells with promoter hypermethylation-mediated SFRP1 downregulation." (PMID 37333823, 2023). "The results reveal that cancer stem cell markers are significantly increased by exogenous SFRP1 treatments, as well as the downstream target genes of the Wnt/-catenin pathway." (PMID 36968194, 2023). "Completed: cfDNA methylatation (RASSF1A, MAL and SFRP1) is a phenotypic feature of BC, and can be used for cancer diagnosis." (PMID 36430675, 2022).
cancer (continued). "This case study of highly specific SFRP1 mimetics with antiproliferative properties demonstrates the potential of this new therapeutic platform in personalized cancer medicine." (PMID 36139547, 2022). "SFRP1 hypermethylation and silencing occur early in the carcinogenesis of most cancers, including PDAC." (PMID 34830873, 2021). "The primary mechanism of SFRP1 is that it protects against carcinogenesis by acting as an antagonist to the oncogenic Wnt/β-catenin pathway involved in both cancer development and embryonic development." (PMID 34830873, 2021). "SFRP1 was also reported to inhibit several cancers, which was mainly due to epigenetic inactivation via DNA methylation or transcriptional silencing by microRNAs." (PMID 34205081, 2021). "The correlation between SFRP1 expression and cancer patients' survival was discordant according to the bioinformatics analyses with Kaplan–Meier Plotter and PrognoScan." (PMID 32764696, 2020). "Our results showed that SFRP1 expression had different clinical applications in all types of human cancer." (PMID 32764696, 2020). "Previously, HDAC inhibitor (HDACi); romidepsin and DNA methyltransferase inhibitor (DNMTi); and 2′-deoxy-5-azacytidine (Decitabine) were used to restore SFRP1 expression in cancer cells (please refer to Section 4 below)." (PMID 32074995, 2020). "Hypermethylation of the SFRP1 promoter has been recognized as a common mechanism for downregulation of this gene in cancers." (PMID 32074995, 2020). "Dysregulation of SFRP1 gene expression is better known in the context of cancer, and SFRP1-promoter hypermethylation and suppression of expression has been associated with several different cancer types." (PMID 32098349, 2020). "SFRP1 is the hinge of WNT- or hedgehog-predominant pathway in cancer, and collaboration of SFRP1 with other signalling pathways is possible." (PMID 32764696, 2020). "Lastly, this review provides directions for future research to advance SFRP1 as a promising cancer biomarker." (PMID 32074995, 2020). "Combination of NDRG4 and SFRP1 is able to predict the response of cancer treatment with a DNA damaging agent, DNA methyltransferase inhibitor, and/or an HDAC inhibitor." (PMID 32074995, 2020). "In other cancers, the incidence of SFRP1 alteration was also low (0.4%–3.0% in these 4 kinds of cancer)." (PMID 32764696, 2020). "Although a lot of progress has been made regarding the regulation and function of SFRP1 in the normal and cancer cells, many questions remain unanswered." (PMID 32074995, 2020). "In 10 other cancer types, the correlation between SFRP1 expression and patient survival was weak, with a wide 95% confidence interval (CI)." (PMID 32764696, 2020). "On the other hand, owing to its dual roles, knockdown of SFRP1 also renders certain cancer cells to be more resistant toward selected chemotherapies as well as radiotherapy." (PMID 32074995, 2020). "The hypermethylated and under-expressed genes included Secreted Fzd-related protein 1 (SFRP1), which was consistent with previous ccRCC studies, and PIC3K2G, which was a known cancer susceptibility gene." (PMID 32832275, 2020). "SFRP1 expression is detected in various types of human cancer, and its clinical impact differs based on the cancer type." (PMID 32764696, 2020). "Given the importance of SFRP1 in cancer-related pathways, HDACi and DNMTi appear as promising epigenetic therapy to reverse SFRP1 methylation." (PMID 32074995, 2020). "Mounting evidence suggests that Sfrp1 hypermethylation is a major mechanism for the down-regulation of Sfrp1 in cancer tissue." (PMID 32484208, 2020). "In the present study, we utilised bioinformatics analysis to investigate SFRP1 function in multiple types of cancers." (PMID 32764696, 2020). "Henceforth, the investigation into the contradictory roles of SFRP1, particularly in cancer prognosis and its pharmacogenomics utilities, are indispensable." (PMID 32074995, 2020).
cancer (continued). "In fact, sFRP1 has protective regulatory Wnt-related effects against carcinomas in various cell types, making this assumption more likely." (PMID 32424558, 2020). "RAB37-mediated SFRP1 secretion suppresses cancer stemness, and dysregulated RAB37-SFRP1 pathway confers cancer stemness via the activation of Wnt signaling." (PMID 31169496, 2019). "The meta-analysis of GSTP1, RUNX3, SOCS1, CDH1 and SFRP1 genes methylation was performed between HBV-positive carcinoma tissues and HBV-negative carcinoma tissues and between HBV-positive adjacent tissues and HBV-negative adjacent tissues." (PMID 31772678, 2019). "Our biochemical and image analyses provide the first compelling evidence that Rab37 regulates SFRP1 for exocytosis to the extracellular compartment leading to inactivation of Wnt signaling and cancer stemness." (PMID 30158579, 2018). "Here, we report a previously uncharacterized mechanism by which Rab37 mediates exocytosis of secreted frizzled-related protein-1 (SFRP1), an extracellular antagonist of Wnt, to suppress Wnt signaling and cancer stemness in vitro and in vivo." (PMID 30158579, 2018). "Recently the anti-proliferative activity of purified SFRP1 was demonstrated in two cancer cell lines, which is important for the development of pharmaceutical interventions." (PMID 30394013, 2018). "Uncovering how JARID2 and SFRP1 modulate cancer progress and patient survival in these cancers will be an important future direction of this study." (PMID 30119689, 2018). "Our findings reveal that Rab37-mediated SFRP1 secretion suppresses cancer stemness, and dysregulated Rab37-SFRP1 pathway confers cancer stemness via the activation of Wnt signaling." (PMID 30158579, 2018). "Since the Wnt signaling is an important regulator of cancer development and progression, the relation of SFRP1 with tumorigenesis has received much attention from the scientific community." (PMID 29610564, 2018). "Here, we report a novel anti-cancer stemness function of Rab37, which mediates secreted frizzled-related protein-1 (SFRP1), an extracellular antagonist of Wnt19–21, for exocytosis to suppress cancer stemness." (PMID 30158579, 2018). "We observed that SFRP1 promoter methylation increased significantly with participant age, which confirms findings in colorectal tissue from healthy and cancer patients." (PMID 28077379, 2017). "This is the first study showing that exercise training leads to decreased serum SFRP1 levels in patients with cancer." (PMID 28178355, 2017). "Recently, the combined usage of two drugs, romidepsin and decitabine, restored SFRP1 activity in four cancer cell lines, A498, KIJ265T, MDA-231, and BT-20." (PMID 27534621, 2016). "One report showed binding of SFRP1 to thrombospondin-1, thereby inhibiting cancer cell adhesion and migration." (PMID 25033833, 2014). "This selection was mainly in view of the pivotal role of these genes in renal function (KCNJ1), cancer (SFRP1) and cell differentiation (TCF21)." (PMID 24194935, 2013). "Studies using various cancer cells have consistently suggested that SFRP1 can function in both a paracrine and autocrine fashion." (PMID 23441124, 2013). "As compare to non-cancer group, higher methylation level of DAPK, IRF8, p14, RASSF1A and SFRP1 were detected in cancer samples." (PMID 21599969, 2011). "Many of the differentially expressed genes are implicated in tumorigenesis, and 5 of the upregulated genes are involved in the WNT pathway (e.g. Fst, Lgr5, Sfrp1, Sfrp2, and Wisp2), which is dysregulated in a variety of cancers." (PMID 20429939, 2010). "Aberrant methylation of the sFRP1 promoter is one of the most consistent alterations in human cancer." (PMID 19473496, 2009). "As known, some groups have reported that SFRP1 as a Wingless-type (Wnt) signaling antagonist is frequently inactivated owing to the promoter methylation in many human cancers." (PMID 17626620, 2007).
cancer (continued). "Secondly hypermethylation of CDH1, CDKN2A, and SFRP1, was rare in PCa tissues (<5% of the specimens), although they were hypermethylated in cancer cell line controls." (PMID 15292941, 2004). "SFRP1 exhibits multiple effects that may be involved in regulating the chemosensitivity of cancer cells." (PMID 40943068, 2025). "One possibility is the potential epigenetic silencing of sFRP1 as observed in cancer cells." (PMID 38722977, 2024). "Additionally, a decreased concentration of SFRP1 has been described in some human cancers, suggesting that SFRP1 suppresses proliferation, migration, and invasion." (PMID 37999144, 2023). "We analyzed migration, invasion, and colony formation to establish whether SFRP1 could boost cancer’s aggressive properties." (PMID 36968194, 2023). "Furthermore, an analysis on the data concerning expression of TCGA COAD mRNA-seq showed that the expression of SFRP1 in cancer tissue was significantly lower than in paracancerous tissue, and the area under ROC was 0.985." (PMID 37859826, 2023). "In summary, overexpression of hcR1445 could inhibit OC growth and OC metastasis in vivo, and hcR1445 works as a cancer suppressor through regulating the miR‐576‐5p/SFRP1 axis in OC." (PMID 36259450, 2023). "A negative association between SFRP1 expression and cancer progression has also been reported, showing that loss of SFRP1 expression is a promoter of theWnt/β-catenin pathway." (PMID 36968194, 2023). "In the present study, we found miR-26a-5p exerted antitumor effects on NSCLC by inhibiting cancer stem-cell like properties through downregulating the DNMT3A to increase SFRP1 expression and then increasing SFRP1 inhibited Wnt/β-catenin pathway in the regulatory process." (PMID 35860691, 2022). "Patients with relatively high SFRP1 expression levels could have a more effective response to immunotherapy, which may be one of the explanations for SFRP1 being shown to have value in predicting cancer progression and prognosis in our analyses." (PMID 35892344, 2022). "Furthermore, forced re-expression of SFRP1 in several cancers induced apoptosis and suppressed cell proliferation, invasion, and transformation both in vivo and in vitro." (PMID 34830873, 2021). "In various human cancers, SFRP1 is transcriptionally silenced via DNA methylation." (PMID 34336665, 2021). "The log2 ratio of SFRP1 expression in cancer vs. normal tissue was calculated." (PMID 32764696, 2020). "However, a high expression level of SFRP1 is correlated with cancer recurrence, peritoneal carcinomatosis and poor prognosis for patients." (PMID 32764696, 2020). "We performed bioinformatics analyses of SFRP1 expression in human cancer." (PMID 32764696, 2020). "However, high expression levels of SFRP1 protein were correlated with cancer recurrence, peritoneal carcinomatosis and poor patient prognosis." (PMID 32764696, 2020). "We also provide the latest evidence of the divergent roles of SFRP1 in tumorigenesis that may encourage the development of novel drugs for cancer treatment by targeting SFRP1." (PMID 32074995, 2020). "However, there are several databases that have shown equivocal correlation between gene expression of SFRP1 and survival of cancer patients." (PMID 32764696, 2020). "The expression level of SFRP1 mRNA was diverse, suggesting that function of SFRP1 may be distinct in different types of cancer." (PMID 32764696, 2020). "The complex function of SFRP1 in human cancer requires further investigation." (PMID 32764696, 2020). "Among the five members of the SFRP family, SFRP1 has been extensively studied in human cancers." (PMID 32074995, 2020). "Hence, restoration of SFRP1 expression via demethylating drugs or over-expression experiments opens the possibility for new cancer therapy approach." (PMID 32074995, 2020).
cancer (continued). "In addition, the proto-oncogene c-Myc is also a key oncogenic component of the WNT/β-catenin signaling pathway through transcriptional repression of the secreted Wnt inhibitors DKK1 and SFRP-1 in cancer cells." (PMID 30348169, 2018). "It will be interesting to study whether additional cargos other than SFRP1 were involved in Rab37-mediated suppression of cancer stemness." (PMID 30158579, 2018). "Finally, we show that JARID2 and SFRP1 are negatively correlated in cancer and correlate with overall survival and life span, suggesting that the repression of SFRP1 by JARID2 has important implications outside of skeletal muscle as well." (PMID 30119689, 2018). "Our results showed that DNA methylation of SFRP1 and SFRP2 might be useful to predict cancer risk of surrounding normal mucosa." (PMID 28533824, 2017). "SFRP1 is located at chromosome 8 p12, a region frequently deleted in human cancers." (PMID 26170835, 2015). "As the reduction of SFRP1 is in line with increased aggressiveness of cancer cells, its overexpression might be an approach to explore novel therapeutic projections." (PMID 25033833, 2014). "Silencing of SFRP1 in cancer has been widely reported, indicating that aberrant inactivation of SFRP1 might be a common mechanism to activate Wnt signaling in solid tumours." (PMID 24594839, 2014). "Additionally, SFRP1 seems to be involved in regulatory processes necessary for tumorigenic cancer cells, e.g. regulation of apoptosis as well as migration and adhesion processes." (PMID 25033833, 2014). "Thus, the knockdown of SFRP1 renders cancer cells more resistant to standard chemotherapeutic treatment." (PMID 25033833, 2014). "However, there is concern that Sfrp1 is a poor drug target based on its broad tissue expression and the link between Wnt signaling and various cancers." (PMID 23300464, 2012). "Expression levels of SHH, PTCH1, and sFRP1 mRNA in cancer samples were analyzed with real-time PCR." (PMID 20230186, 2010). "It is well established that de-regulated expression and altered function of the genes involved in cell-cycle regulation and death contribute to the pathogenesis of cancer and SFRP1 exhibits an apoptotic function in several different tissues, including breast epithelial cells." (PMID 19422694, 2009). "In addition, ERK1/2 pathway activity is also decreased by sFRP1 treatment in the majority of the cancer cells, with SkBr3 cells being particularly sensitive." (PMID 17897439, 2007). "Importantly, in the literature, the level of SFRP1 was different for various cancers." (PMID 37999144, 2023). "Though the new 33 CMT cohort had mixed grades and unknown ER/PR status, all cases within our previous cohort of 27 CMTs were higher grade ERneg cancer so that SFRP1 suppression is likely to have an additional role to possibly enhancing ER-signalling in our new cohort." (PMID 37402051, 2023). "Molecular subtypes of cancer may alter the regulatory system of SFRP1." (PMID 32764696, 2020). "However, sFRP1 also negatively regulates tumorigenesis and cancer progression." (PMID 32293507, 2020). "It has also been proven that in CRC, even though cancer-associated nonsense mutation that prematurely terminates protein translation at codon 151 (N150) was identified, point mutation is not the primary cause of SFRP1 inactivation." (PMID 32074995, 2020). "Our results indicate that DKK1 and SFRP1 may be potentially useful biomarkers for evaluating the beneficial effects of long-term exercise on physical fitness and metabolism as well as the prognosis of patients with cancer." (PMID 28178355, 2017). "Point mutation is not a frequent method of inactivation of the SFRP1 gene in cancer." (PMID 26170835, 2015). "However, regarding the reported Wnt pathway activation in CML cancer stem cells and the reported correlation of SFRP-1 promoter methylation and resistance to imatinib the impact of hypermethylation-associated gene silencing in CML in contrast to Ph-MPN has to be further elucidated." (PMID 22935201, 2012).